ERBB3 (erb-b2 receptor tyrosine kinase 3)
Diseases named in the same sentence as ERBB3 in open-access papers (continued):
Sharing a sentence is not in itself a finding about the gene and the disease.
liposarcoma (2 papers, 2021 to 2024). A usually painless malignant tumor that arises from adipose tissue. "Receptor tyrosine kinase (RTK) genes DDR2 (discoidin domain receptor tyrosine kinase 2), ERBB3 (Erb-B2 receptor tyrosine kinase 3), FGFR1 (fibroblast growth factor receptor 1), and ROS1 (ROS Proto-Oncogene 1) are also amplified in dedifferentiated liposarcoma." (PMID 33498189, 2021).
multiple sclerosis (2 papers, 2015 to 2023). A progressive autoimmune disorder affecting the central nervous system resulting in demyelination. "Furthermore, downregulation of ErbB-2 and ErbB-3 genes is associated with neuro-degenerative diseases such as multiple sclerosis and Alzheimer's disease." (PMID 26559525, 2015).
oesophageal cancer (2 papers, 2016 to 2020). "ErbB3 expression, for example, has been increasingly characterised in oesophageal cancers and is associated with poor prognosis." (PMID 31765988, 2020).
papillary carcinoma (2 papers, 2022). A malignant epithelial neoplasm characterized by a papillary growth pattern. "ERBB3/ERBB4/RAF1 kinases were activated in papillary carcinoma compared to other variants, PAK3/PAK6/CDK1 kinases were activated in NOS, and PRKACA/PRKACB/PRKACG kinases were activated in differentiation variants." (PMID 35659036, 2022). "The results showed that papillary carcinoma was characterized by a low immune score, increased metabolism-related pathways, and the activated ERBB3/ERBB4 kinases." (PMID 35659036, 2022).
Pleural effusion (2 papers, 2013 to 2016). The presence of an excessive amount of fluid in the pleural cavity. "In this study we demonstrated, in a set of malignant pleural effusion-derived cultures of NSCLC, the synergistic antitumor effect of a histone deacetylase inhibitor (HDACi), such as vorinostat or valproic acid (VPA), in combination with the anti-ErbB3 monoclonal antibody (MoAb) A3." (PMID 26862736, 2016).
psoriasis (2 papers, 2021 to 2025). An autoimmune condition characterized by red, well-delineated plaques with silvery scales that are usually on the extensor surfaces and scalp. "Concerning miRNAs, it has been identified that hsa-miR-19a-3p has great potential to become a biomarker for psoriasis because it binds to the mRNA of seven genes (CAST, TSC1, SPATA2, ERAP1, TNIP1, ERBB3 and SDC4) thatare associated with psoriasis." (PMID 40725409, 2025).
pulmonary arterial hypertension (2 papers, 2024 to 2025). Pulmonary arterial hypertension (PAH) is a group of diseases characterized by mean pulmonary artery pressure >20 mmHg and elevated pulmonary arterial resistance leading to right heart failure. "In pathological conditions such as pulmonary arterial hypertension, upregulated ErbB3 promotes endothelial dysfunction, whereas ErbB3 knockout alleviates vascular lesions." (PMID 41438739, 2025). "In individuals with pulmonary hypertension, elevated levels of human epidermal growth factor receptor 3 (ErbB3), also known as HER3, were observed in the lungs, serum, and distal pulmonary arteries compared with healthy controls." (PMID 39040847, 2024).
rhabdomyosarcoma (2 papers, 2012 to 2018). A rare aggressive malignant mesenchymal neoplasm arising from skeletal muscle. "Finally, to address the effects of both gain-of-function and loss-of-function of ERBB3 for the growth of rhabdomyosarcoma cells, RD cell transfectants overexpressing ERBB3 or with siRNA-targeted ERBB3 were analyzed using MTT assays measuring the amount of viable cells." (PMID 23227212, 2012). "The overexpression of ERBB3 seemed to be relatively specific for the alveolar subtype of pediatric rhabdomyosarcoma." (PMID 23227212, 2012). "Analysis of the Genesapiens database of human transcriptomes demonstrated statistically significant up-regulation of VEGFC and EPHA2 in Ewing’s sarcoma, and ERBB3 in alveolar rhabdomyosarcomas." (PMID 23227212, 2012). "In contrast, EGFR (epidermal growth factor receptor), VEGFR2 (VEGF receptor 2 = KDR), and PDGFRA (platelet-derived growth factor receptor α) were overexpressed in embryonal, and ERBB3 (ErbB3) in alveolar and unclassified rhabdomyosarcomas." (PMID 23227212, 2012). "In summary, we found that EPHA2 and VEGFC are highly expressed in pediatric Ewing’s sarcomas and ERBB3 in pediatric rhabdomyosarcomas." (PMID 23227212, 2012). "The data were validated by demonstrating ErbB3 protein expression in clinical rhabdomyosarcoma and suppression of rhabdomyosarcoma cell growth by RNA interference-mediated down-regulation of ErbB3." (PMID 23227212, 2012). "ERBB3 overexpression promoted whereas ERBB3-targeted siRNA suppressed rhabdomyosarcoma cell gowth, indicating a functional role for ErbB3 signaling in rhabdomyosarcoma." (PMID 23227212, 2012). "In silico data for ERBB3 was validated by demonstrating ErbB3 protein expression in pediatric rhabdomyosarcoma in vitro and in vivo." (PMID 23227212, 2012). "Finally, we found that ERBB3 (HER3) transcript is highly expressed in pediatric alveolar rhabdomyosarcomas." (PMID 23227212, 2012). "Down-regulation of ErbB3 levels also led to suppression of rhabdomyosarcoma cell growth in vitro." (PMID 23227212, 2012). "Taken together, these findings indicated that, consistent with the data from the in silico approach, ErbB3 protein was expressed in a subpopulation of pediatric alveolar rhabdomyosarcoma patients, and that ErbB3 expressed in RD cells was biologically significant in promoting growth." (PMID 23227212, 2012). "When ten clinical samples representing pediatric alveolar rhabdomyosarcoma were analyzed for ErbB3 expression, strong cytoplasmic expression was detected in one, and weak to moderate expression in two, whereas seven samples demonstrated no expression (data not shown)." (PMID 23227212, 2012). "While the percentage of ErbB3-positive alveolar rhabdomyosarcomas needs to be verified in larger clinical series, our findings suggest that ErbB3 targeting could be effective only for a subpopulation of patients, and ErbB3 immunohistochemistry considered as a predictive test." (PMID 23227212, 2012). "The relative overexpression of ERBB3 in alveolar and in unclassified (not otherwise specified) rhabdomyosarcoma samples was 5-fold (P = 0.04) and 8-fold (P<0.001), respectively." (PMID 23227212, 2012). "Six out of six analyzed Ewing’s sarcoma samples were totally negative for ErbB3 immunoreactivity, indicating specificity of ErbB3 overexpression in pediatric rhabdomyosarcoma, and consistent with the in silico findings." (PMID 23227212, 2012).
schwannoma (2 papers, 2013 to 2017). A benign, usually encapsulated slow growing tumor composed of Schwann cells. "In contrast to ErbB2 and ErbB3, EGFR (another receptor of this family) was downregulated in schwannomas (−17.3-fold, p=2.26e-12)." (PMID 23354516, 2013). "In schwannoma cells lacking NF2, epidermal growth factor receptor tyrosine kinases ErbB2, ErbB3 and EFGR are overabundant on the cell surface, upregulating their downstream targets, thereby driving cell proliferation." (PMID 28821767, 2017).
serous carcinoma (2 papers, 2023 to 2025). "In contrast, ERBB3, FOLR1, and NaPi2b expression levels are higher in serous carcinoma than in endometrioid carcinoma." (PMID 40046734, 2025).
abscess (1 paper, 2017). An inflammatory process characterized by the accumulation of pus within a newly formed tissue cavity which is the result of a bacterial, fungal, or parasitic infection or the presence of a foreign body. "Our results indicate that Tasmanian devils without injuries or an isolated skin lesion have serum ERBB3 levels <30 pg/ml whereas Tasmanian devils with multiple injuries or large abscesses have serum ERBB3 levels ranging from 92–663 pg/ml." (PMID 28591206, 2017).
adenosarcoma (1 paper, 2017). A low grade malignant neoplasm characterized by the presence of a benign epithelial component (tubular and cleft-like glands) and a low grade sarcomatous component that contains varying amounts of fibrous and smooth muscle tissues. "In our cohort of adenosarcomas, we detected alterations in PI3K pathway in 26% (5/19) of cases (PIK3CA, PIK3CG, PIK3R1, PTEN mutations and/or amplification of AKT2 or ERBB3)." (PMID 28267263, 2017).
alopecia (1 paper, 2017). Hair loss usually from the scalp. "We noted that devils with widespread alopecia (devils 24, 29, 33 and 35), did exhibit increased serum ERBB3 levels ranging from 4383–20,021 pg/ml, suggesting that the severity of CL manifesting clinically as widespread alopecia may contribute to increased serum ERBB3 levels." (PMID 28591206, 2017).
atherosclerosis (1 paper, 2022). A disease characterized by the build-up of fatty material and calcium deposition in the arterial wall resulting in partial or complete occlusion of the arterial lumen. "Stimulation of ErbB3 by NRG1β has been reported to inhibit EC proliferation, and ErbB3 may be a potential therapeutic target of the NRG1-ErbB pathway against atherosclerosis." (PMID 36120374, 2022).
bile duct tumors (1 paper, 2024). "For the ERBB3–EGFR complex, the interface mutation with the highest frequency for ERBB3 is observed in 0.006% of the samples and they are from endometrium, large intestine, and bile duct tumors." (PMID 38216592, 2024).
bone metastasis (1 paper, 2021). Transfer of a neoplasm from its primary site to bones. "By incorporating EGFR, ERBB2, and ERBB3 expression in a decision tree model, four ERBB receptor status groups could be developed to segregate patients based on the risk of developing bone metastasis." (PMID 33918389, 2021).
chondrosarcoma (1 paper, 2020). A malignant cartilaginous matrix-producing mesenchymal neoplasm arising from the bone and soft tissue. "BCAR4 was also reported to promote chondrosarcoma cell proliferation through activation of mTOR19, a downstream target of ERBB2/ERBB3 signalling." (PMID 32193429, 2020).
chordoma (1 paper, 2021). Chordomas are rare malignant tumors arising from embryonic remnants of the notochord in axial skeleton. "Genomic copy-number duplication of HER3 (ERBB3) has been reported in chordoma recently." (PMID 34868903, 2021). "Furthermore, EGFR activation has also been reported, and an European multi-center trial is evaluating the efficacy of afatinib, an ERBB family (EGFR/ERBB1, HER2/ERBB2, ERBB3, and ERBB4) inhibitor, as first-line or later-line treatment in advanced chordoma (NCT03083678)." (PMID 34868903, 2021).
cyst (1 paper, 2016). A sac-like closed membranous structure that may be empty or contain fluid or amorphous material. "However, in the presence of HRG, ErbB3 depletion fully restored polarized cyst structure and lumen formation to the level seen in the control." (PMID 27447549, 2016).
diverticular disease (1 paper, 2019). A complex disorder characterised by mucosal outpouchings (diverticulae) of the colonic wall which can become infected and inflamed leading to diverticulitis, perforation and bleeding. "Further studies are required to unravel whether a deficiency of the NRG1/ErbB2/ErbB3 system observed in DD may also occur in asymptomatic diverticulosis." (PMID 31920561, 2019). "As diverticular disease (DD) is associated with intestinal hypoganglionosis, the NRG1-ErbB2/ErbB3 system and the nAChR were studied in patients with DD and controls." (PMID 31920561, 2019).
E. coli infection (1 paper, 2018). "We therefore investigated the possible dimerization forms in response to meningitic E. coli infection, and an obvious heterodimerization of EGFR and ErbB3 was observed in the hBMECs upon infection." (PMID 30687645, 2018). "At this time point, it is hard to tell whether the delayed EGFR phosphorylation we observed results from insufficient knock-down of ErbB3, or whether some degree of EGFR homodimerization existed in the hBMECs in response to meningitic E. coli infection." (PMID 30687645, 2018).
endometrioid ovarian carcinoma (1 paper, 2020). "A maximum of six mutations was present in one patient with endometrioid ovarian carcinoma (MSH6, PIK3CA, FBXW7, PIK3R1, PITCH1, ERBB3 and PPP2R1A)." (PMID 32120793, 2020).
esophageal squamous cell carcinoma (1 paper, 2021). Esophageal squamous cell carcinoma (ESCC) is a type of esophageal carcinoma (EC) that can affect any part of the esophagus, but is usually located in the upper or middle third. "They further confirmed that ERBB3 silencing decreased PI3K and AKT phosphorylation upregulated by HOXC10 and significantly reduced esophageal squamous cell carcinoma cells proliferative capacity." (PMID 34113572, 2021).
gallbladder tumors (1 paper, 2024). "Using mouse and cell culture models, a study found that gallbladder tumors or cancer cells harboring ERBB2/ERBB3 mutations showed an enhanced effect of anti-PD-1 treatment compared to WT43." (PMID 38502852, 2024).
inflammatory bowel disease (1 paper, 2025). A spectrum of small and large bowel inflammatory diseases of unknown etiology. "In inflammatory bowel disease, upregulation of the NRG1/ERBB3 axis activates PI3K/Akt signaling, sustaining intestinal epithelial proliferation and damage repair." (PMID 41178971, 2025).
intestinal polyp (1 paper, 2021). Discrete abnormal tissue masses that protrude into the lumen of the intestine. "The decrease of polyp number and polyp size in the double knockout of Egfr and Erbb3 suggests these two receptors are essential for the development of intestinal polyps." (PMID 34843459, 2021). "To confirm a previous study showing intestinal polyps are dependent upon ERBB3, we generated an intestinal epithelia-specific ERBB3 deletion in C57BL/6-ApcMin/+ mice." (PMID 34843459, 2021). "Contrary to the previous report showing a significant reduction in intestinal polyps with ablation of ERBB3 on a B6;129 mixed genetic background, we observed a significant increase in polyp number with ablation of ERBB3 on C57BL/6J compared to control littermates." (PMID 34843459, 2021). "This current study used a different genetic background (C57BL/6J) from the previous study (B6;129 mix) that reported reduced intestinal polyps with loss of ERBB3, suggesting a genetic background-dependent effect of ERBB3 on the development of intestinal polyps." (PMID 34843459, 2021). "We examined intestinal polyp development in the absence of ERBB3 activity using intestinal epithelial-specific deletion of Erbb3." (PMID 34843459, 2021).
lactic acidosis (1 paper, 2008). Metabolic acidosis characterized by the accumulation of lactate in the body. "We further confirmed the induction of ERBB3, CD55, and PLAUR in response to lactic acidosis, and to the combination of hypoxia with lactic acidosis, via real-time PCR." (PMID 19057672, 2008). "Genes induced by lactic acidosis included: PLAUR, ERBB3, CD55, interleukin 15, CXCL16, angiogenin and MHC class I genes." (PMID 19057672, 2008).
liver steatosis (1 paper, 2022). "ERBB3 could be modulated through phosphorylation by NRG1 to alleviate liver steatosis." (PMID 35678936, 2022). "The other promising genes and proteins that may play important roles in mediating the reduction of liver steatosis by soy protein include hepatic Neuregulin 1 (NRG1), Erb-B2 Receptor Tyrosine Kinase 3 (ERBB3) and mitogen-activated protein kinase interacting serine/threonine kinase 1 (MKNK1)." (PMID 35678936, 2022).
mastitis (1 paper, 2020). Inflammation of breast tissue during lactation or postpartum due to an obstructed duct or infection. "Additionally, some of the highly connected genes belonging to this module have been found by others to be related to mastitis development, immune response or mammary gland development including FYN, CDH11, CAV1, F11R, ZEB1, ERBB2, and ERBB3." (PMID 32754201, 2020).
mesenchymal tumors (1 paper, 2014). "An analysis of the Cancer Genome Atlas (TCGA) HNSCC dataset confirms enrichment for ErbB3 activity in mesenchymal tumors." (PMID 25238142, 2014).
migraine (1 paper, 2022). "Among the identified 36 blood proteins with pleiotropic effects on migraine at SNPs within LD-independent loci, five proteins have two or more pleiotropic SNPs with migraine, including four SNPs for ERBB3, three SNPs for F2R, and two SNPs for B3GNT2, VEGFA and SCARF2." (PMID 35546551, 2022).
myocardial disease (1 paper, 2024). "This is particularly interesting as cardiotoxicity is known to arise from cancer therapies targeting ERBB3 (and related family members) and because other studies have implicated HSPA2 in other forms of myocardial disease." (PMID 39180332, 2024).
osteoarthritis (1 paper, 2025). A noninflammatory degenerative joint disease occurring chiefly in older persons, characterized by degeneration of the articular cartilage, hypertrophy of bone at the margins and changes in the synovial membrane. "Focusing on osteoarthritis treatment, β-hydroxybutyrate has been demonstrated to ameliorate osteoarthritis through the activation of the ERBB3 signaling pathway in mice." (PMID 40027098, 2025).
pancreatitis (1 paper, 2022). Inflammation of the pancreas. "The autocrine loop of Nrg-1/2 with ErbB2/ErbB3 heterodimer elucidates the activation of downstream pathways and their crosstalk with one another as a key event in the conversion of normal stem cells into CSCs under inflammatory microenvironments such as pancreatitis." (PMID 35177646, 2022).
polyp (1 paper, 2021). A usually exophytic mass attached to the underlying tissue by a broad base or a thin stalk. "To elucidate the mechanism underlying the differentially effect of ERBB3 loss on polyp number and size, we investigated cell proliferation and death in polyps and adjacent normal epithelia." (PMID 34843459, 2021). "Due to this background dependency, which is reminiscent of the background sensitivity of EGFR on polyp induction, we further show that the enhanced polyp number on the C57BL/6J background can be eliminated in a double deficiency of EGFR and ERBB3 in the intestinal epithelium." (PMID 34843459, 2021).
sarcomatoid carcinoma (1 paper, 2018). A malignant epithelial neoplasm characterized by the presence of spindle cells and anaplastic morphologic features.
signet ring cell carcinoma (1 paper, 2011). A usually aggressive, poorly differentiated invasive adenocarcinoma characterized by the presence of malignant glandular cells in which the nucleus is pressed to one side by the presence of intracytoplasmic mucus. "In many of the signet ring cell carcinoma cell lines, the ErbB2/ErbB3 pathway is often constitutively activated by the autocrine loop of ErbB2-ErbB3-Muc4-ErbB2." (PMID 22216327, 2011). "It appears that there are two types of signet ring carcinomas: ErbB2/ERbB3 activated and non-activated." (PMID 22216327, 2011).
skin abscesses (1 paper, 2017). "Wild caught devils 6 and 7 were unremarkable and had serum ERBB3 levels <30 pg/ml however devil 9 (220 pg/ml) and devil 10 (92 pg/ml) both recorded skin abscesses." (PMID 28591206, 2017).
Ta (1 paper, 2024). "Our analysis identified two subgroups in Ta tumors: one with FGFR3 alterations linked to LG tumors and favorable outcomes, and another with alterations in ERBB2, PIK3CA, and ERBB3 mutations, and FGFR1, CCND1, and MYC amplifications, associated mostly with HG tumors and poorer prognosis." (PMID 39410541, 2024).